HDAC1 (histone deacetylase 1)
Diseases named in the same sentence as HDAC1 in open-access papers (continued):
Sharing a sentence is not in itself a finding about the gene and the disease.
tumor (continued). "In summary, our current study found that the anti-tumor effect of CHI was partly depended on the expression of HDAC1 in MM cells and CHI combined with BTZ exhibited synergistic effect in antagonizing MM cell growth in vitro and in vivo." (PMID 34539893, 2021). "Moderate cytoplasmic HDAC-1 IRS was observed in cases with increased tumor size (Mann–Whitney U test, p = 0.03) and marginally more frequently in cases with gain of chromosome 8q (40% vs. 4% Fischer’s exact test, p = 0.07)." (PMID 34638249, 2021). "After silencing HOXA10, the results revealed that tumor growth was slowed while tumor weight was markedly diminished, while tumor growth was accelerated and the weight significantly elevated following HDAC1 overexpression." (PMID 33596966, 2021). "BoHV-1 infection reduced the protein levels of histone deacetylases (HDACs), including HDAC1-4 that are promising anti-tumor drug targets." (PMID 34445287, 2021). "In this study, we determined that CHI exhibited significant anti-tumor effect on MM cells both in vitro and in vivo, which was positively correlated with the expression of HDAC1." (PMID 34539893, 2021). "RBBP4 expression is higher in triple-negative and HER2-positive tumours in comparison with luminal A and luminal B tumours, correlates positively with HDAC1 expression, and correlates negatively with ER and PR expression." (PMID 34073937, 2021). "We had already observed that HDACi class I inhibit an EWS-FLI1-specific expression profile and that the elimination of HDAC1 and HDAC2 reduces the tumor susceptibility of EwS cells." (PMID 34654445, 2021). "HDAC1 knockdown resulted in a significant lag in tumor growth with both shRNAs, which was maintained throughout the study." (PMID 34494550, 2021). "HOXA10-induced upregulation of HDAC1 interacts with DNMT1-KLF4 axis, while the inhibition of HOXA10 or HDAC1 represents a promising anti-tumor therapy target for LAD." (PMID 33596966, 2021). "For HDAC1, a well‐known histone deacetylase, a number of studies have validated its crucial role in tumor progression." (PMID 33459509, 2021). "In animal models, the depletion of CHD4 affected CRC tumor growth, and the combination of a histone deacetylase 1 (HDAC1) inhibitor and platinum drugs inhibited CHD4 expression and increased the cytotoxicity of platinum drugs." (PMID 33994851, 2021). "In contrast, a correlation between advanced tumour stages and decreased HDAC1 expression has been observed in OSCC." (PMID 34439236, 2021). "HDAC1 functions as a tumour suppressor by restraining the activity of PML-RAR in the preleukaemic stage of APL." (PMID 34395273, 2021). "Simultaneous inhibition of DNMT1/HDAC1 can play a synergistic role in improving anti-tumor drugs’ therapeutic effects and reducing the incidence of drug resistance." (PMID 34073721, 2021). "Immunohistochemistry was used to detect the expression levels of HDAC1, cleaved caspase-3, Bcl-2 and Bax in H226 and H520 CDXs tumor cells." (PMID 32903420, 2020). "We also verified that HDAC1, 2, 7, 8, and 11 were significantly upregulated in NS tumor samples compared to SEs." (PMID 33050470, 2020). "Collectively, our findings suggest FMNL1 works with HDAC1 to induce the expression of CXCR2 to promote tumor metastasis." (PMID 33324547, 2020). "A large number of researches have proven that significant nuclear expression of histone deacetylase 1 (HDAC1) occurred in GBM cells during the process of tumor progression, recurrence, and metastasis." (PMID 32219100, 2020). "HDAC1 has oncogenic activity in tumor cells, but can have different functions in different subpopulations, but the combined genetic deletion of HDAC1 and HDAC2 results in accelerated leukemogenesis." (PMID 32585896, 2020).
tumor (continued). "In esophageal cancer, combinations of quercetin and sodium butyrate repress tumor growth and cell proliferation which was associated with downregulation of DNMT1, NF-κBp65, HDAC1, and cyclin D1." (PMID 30881375, 2019). "Previously, studies have shown that the inhibition of HDAC1 regulated the apoptosis of tumor cells, as well as that of AML cells, by affecting its target genes." (PMID 31358016, 2019). "The activation of HDAC1 uniquely in the EBV positive tumors also suggests the importance of epigenetic regulation during tumor formation." (PMID 31584998, 2019). "HDACs inhibited by Panobinostat remarkably improved the inhibitory effect of doxorubicin on tumor growth in vivo, including tumor growth rates and volumes, while HDAC1 overexpression significantly increased doxorubicin resistance." (PMID 31358016, 2019). "EIF3I plays a crucial role in the initiation of protein synthesis, whereas HDAC1 interacts with the retinoblastoma tumor-suppressor protein to control cell proliferation and differentiation." (PMID 31253147, 2019). "By interacting with MAD2L1, HDAC1, and histone deacetylase 276,77, this protein likely plays a role in cell cycle control and tumor suppression." (PMID 30531795, 2018). "MiR-584-5p imparts its tumor-suppressing and therapy-potentiating effects by targeting eIF4E3, HDAC1, and c-Myc in MB." (PMID 30382096, 2018). "Higher levels of HDAC1 and HDAC2 expression are significantly associated with tumor differentiation." (PMID 29899271, 2018). "MiR-584-5p mediated its tumor suppressor and therapy-sensitizing effects by targeting HDAC1 and eIF4E3." (PMID 30382096, 2018). "Taken together, our results suggested that miR-584-5p inhibits MB growth and progression by inhibiting the tumor-promoting function of HDAC1 or eIF4E3." (PMID 30382096, 2018). "Our study provides novel insights into the tumor suppressive role of zebrafish Rb1 and its candidate interacting proteins Rbbp4 and Hdac1 in driving persistent tumor growth, and identifies Rbbp4 as a potential target to inhibit tumor cell survival." (PMID 29914980, 2018). "To evaluate the effect of HDACs ablation on tumor growth in vivo, we grafted the stable HDAC1/2-deficient and control Med1-MB cells into flanks of athymic nude CD1 mice and monitored the growth of the tumor volume over time." (PMID 28276480, 2017). "Earlier, it was shown that maspin expression in tumor cells reverted the cells to an epithelial-like phenotype due to the reprogramming of a small subset of HDAC1 target genes." (PMID 28009978, 2017). "In this study, we found that YY1 expression exhibited a positive correlation with HDAC1 in cell lines and tumor tissues of HCC." (PMID 28489564, 2017). "Several studies have outlined the importance of DNMT1 and HDAC1 in tumor cell growth and development, hence the use of epigenetic inhibitors in the clinic." (PMID 28534825, 2017). "Intracellular maspin was shown to specifically inhibit HDAC1 and consequently to reprogram tumor cells gene expression profile towards a less motile and invasive phenotype." (PMID 28009978, 2017).
tumor (continued). "Overexpression of GGTase-Iβ or constitutively active RhoA abolished the enhancement by inhibiting HDAC1 on anti-tumor effects of statins." (PMID 28481295, 2017). "The present study showed that tumor cell inoculation in tibia induced significantly increased expression of HDAC1 in the microglia and neurons in the SDH, with HDAC2 increased markedly in astrocytes." (PMID 29096654, 2017). "Our results describe the pro-oncogenic roles of Hdac1 and Hdac2 in Eμ-myc tumorigenesis and tumor maintenance and support the clinical use of HDACis." (PMID 27886239, 2016). "In conclusion, our results demonstrate that Hdac1 and Hdac2 promote tumor initiation and progression in Eμ-myc mice and that they impact on proliferation and apoptosis." (PMID 27886239, 2016). "Our findings demonstrate that loss of Hdac1 and Hdac2 has a direct impact on Eμ-myc tg B cells and demonstrate a critical pro-oncogenic role of Hdac1 and Hdac2 in Eμ-myc tumor progression." (PMID 27886239, 2016). "This transplantation assay clearly demonstrates that conditional ablation of both Hdac1 and Hdac2 directly impacts on existing tumor cells and delays tumor appearance." (PMID 27886239, 2016). "Then, we tested the role of HDAC1 in inducing tumor cell invasion in GBC cells via genetic elimination inhibition." (PMID 27092878, 2016). "Inhibitory effect of SNOH-3 and dual combination on HDAC was confirmed by testing the expression levels of HDAC1, Ac-H3, and p21 in tumor cells obtained from xenografts." (PMID 26794658, 2016). "Our transplantation experiment clearly demonstrates that conditional ablation of both Hdac1 and Hdac2 has a direct impact on existing tumor cells, since we observed significantly delayed tumor appearance." (PMID 27886239, 2016). "We demonstrate that Hdac1 and Hdac2 have a pro-oncogenic role in both Eμ-myc tumorigenesis and tumor maintenance." (PMID 27886239, 2016). "MTA1 increases the expression of histone deacetylase-1 and causes deacetylation of HIF-1α, which is involved in tumor angiogenesis." (PMID 26878004, 2016). "In order to discriminate between indirect B cell developmental defects and direct effects of Hdac1 and Hdac2 ablation, we investigating the role of Hdac1 and Hdac2 in existing tumor cells." (PMID 27886239, 2016). "Here, we show that Hdac1 and Hdac2 have tumor-promoting roles in both Eμ-myc tumorigenesis and tumor maintenance." (PMID 27886239, 2016). "HDAC1 expression in tumor targets treated with siRNA targeting HDAC1 was significantly decreased at the end of treatment compared with targets exposed to control siRNA." (PMID 26862729, 2016). "We additionally report apreviously unappreciated tumour suppressor function for hepatocellular nfkb1operating via p50:p50 dimers and the co-repressor HDAC1." (PMID 25879839, 2015). "Results showed that the tumor weights and growth rates of mice injected with Klf4-overexpressed or HDAC1-inhibited cells were significantly lower than those of the control group." (PMID 25341045, 2014). "High grade tumours in combination with high expression of HDAC-1 showed a worse prognosis than the other tumours." (PMID 24624923, 2014). "Molecular silencing of HDAC1 significantly diminished HDACIs-mediated inhibition of tumor cell growth, consistent with decrease of P50 and c-FLIP expression." (PMID 25477070, 2014). "For HDAC-1 40% of the tumours showed high expression levels, for HDAC-2 42% and for HDAC-3 even 59%." (PMID 24624923, 2014). "The combination of high-grade tumours and high expression levels of HDAC-1 was a predictor of PFS (hazard ratio [HR], 1.640; 95% confidence interval [95% CI], 1.021-2.636; p = 0.044)." (PMID 24624923, 2014). "In vivo, oral VPA treatment significantly retarded tumor growth and induced in situ apoptosis, consistent with inhibition of HDAC1/P50/c-FLIP axis and increase of TRAIL/DR5 expression." (PMID 25477070, 2014).
tumor (continued). "Molecular silencing of HDAC1 by siRNA mimicked the effect of HDACIs on tumor cell growth, as well as on P50 and c-FLIP downregulation." (PMID 25477070, 2014). "Patients with high-grade tumours and high expression levels of HDAC-1 were more likely to progress compared to all other patients (p < 0.05)." (PMID 24624923, 2014). "Maspin, a multifaceted tumor suppressor, belongs to the serine protease inhibitor superfamily, but only inhibits serine protease-like enzymes such as histone deacetylase 1 (HDAC1)." (PMID 24278104, 2013). "It is known that the c-Myc/Skp2/Fbw7α and HDAC1/HDAC2 pathways, are associated with tumor progression." (PMID 24265759, 2013). "HDAC1 inactivation resulted in regression of tumor cell growth and activation of caspase-independent autophagic cell death, via LC3B-II activation pathway in Hep3B cells." (PMID 22496786, 2012). "HDAC1 depletion resulted in the significant reduction of tumor cell growth (HepG2, Hep3B and SNU449)." (PMID 22496786, 2012). "Published data indicate that HDAC1 knockdown by siRNA induces a mitotic defect, cell growth inhibition, and an increased percentage of apoptotic cells in human tumor cells." (PMID 20609223, 2010). "Aberrant expression of HDAC1, 2, 3 and 6 has been observed in various tumor types, and HDAC2-mutant mice display reduced tumor development." (PMID 18789133, 2008). "High rates of HDAC1 and HDAC2 expression were significantly associated with tumour dedifferentiation." (PMID 18212746, 2008). "Analysis of xenograft tumours from R306465-treated mice revealed events consistent with HDAC1 inhibition." (PMID 18000499, 2007). "Treatment of tumour-bearing mice with HDAC1 inhibitors results in de-repression of the p21waf1, cip1 gene and induction of fluorescence in vivo." (PMID 18000499, 2007). "HDAC1, linked to higher tumor grades and worse prognosis, has a nonredundant critical involvement in the proliferative potential of GSCs." (PMID 40565099, 2025). "After the test, it was found that DNMT1 and HDAC1/2 in the tumor tissue were significantly downregulated, while the transcriptional levels of pro-apoptotic genes such as BAX, BNIP3, and APAF1 were significantly increased, and the tumor volume was significantly reduced." (PMID 41335282, 2025). "Together, these data suggest that loss of HDAC1 protein and activity results in a shift of the immunophenotype of ALK+ tumor cells, with higher numbers of cells expressing the TCR, seemingly facilitating increased tumor cell dissemination." (PMID 40175628, 2025). "Notably, the combination of EA with the HDAC1 inhibitor precipitated the most pronounced tumor shrinkage." (PMID 40475010, 2025). "To address these limitations, we hypothesized that a class I‐selective HDAC1 inhibitor with optimized pharmacokinetics could achieve dual tumor‐intrinsic and immune‐modulatory effects." (PMID 41267925, 2025). "Indeed, in a previous study, we identified several hundred differentially acetylated proteins, including chromatin-modifying proteins and transcription factors, in mouse NPM::ALK tumor cell lines depleted for HDAC1." (PMID 40175628, 2025). "Chidamide, a novel histone deacetylase (HDAC) inhibitor that targets HDAC1, 2, 3, and 10, demonstrated robust antitumor activity by inducing tumor cell apoptosis and differentiation, inhibiting tumor angiogenesis and metastasis, and enhancing the immune system’s cytotoxic effect on tumors." (PMID 40919161, 2025). "In tumor-bearing mice, HDAC1 deletion promoted the activation of cDC1 and CTL in TIME." (PMID 40165290, 2025). "Furthermore, in this context, the role of other tumour-specific biomarkers needs to be evaluated to identify the potential relationship between HDAC1 and NEP." (PMID 40581884, 2025). "To investigate the potential impact of IHCH9033 treatment on AML patients, we executed comparable gene expression analysis of these class I HDAC members between AML tumor and normal tissues, revealing that HDAC1, HDAC2 and HDAC3 were notably overexpressed in AML." (PMID 39955584, 2025).
tumor (continued). "Furthermore, we noticed decreased infiltration of neutrophils in the tumor microenvironment when HDAC1 or ZEB1 was blocked." (PMID 40924501, 2025). "Generated hbl cell lines express high levels of HDAC1 and form HDAC1-positive tumor clusters." (PMID 39001363, 2024). "TCGA database also shows that HDAC1 expression is higher in tumor samples." (PMID 39075515, 2024). "As an HDAC1 inhibitor, Paromomycin may impact gene expression, metabolic responses, and anti-tumor activity related to exercise adaptation." (PMID 39723246, 2024). "Notably, PHF12 exhibited a substantial upregulation within tumor tissue, concomitant with its correlation to HDAC1." (PMID 39075515, 2024). "Research suggests that Paromomycin may inhibit HDAC1 activity, altering the epigenetic state of tumor cells and thereby reducing their proliferation and invasiveness." (PMID 39723246, 2024). "Second, through the analysis of hypomorphic alleles, we have uncovered a hidden function of lin as a tumor suppressor gene that would otherwise be masked by the pleiotropic effect of a strong/null allele, akin to several gene dosage-dependent tumor suppressors such as ATR, HDAC1/2, and Dicer." (PMID 39137945, 2024). "The HDAC1 may activate the HIF1α/vascular endothelial growth factor A signaling pathway by directly inhibiting the ubiquitination of HIF1α, which can promote tumor angiogenesis." (PMID 39876842, 2024). "Moreover, the proportion of tumor grade was significantly different between the two groups, with the high-HDAC1 group having a higher proportion of WHO grade 4 (GBM) (80.25%) than the low-HDAC1 group did (9.88%)." (PMID 39595109, 2024). "This regulatory approach may aid in understanding the complex interactions between HDAC1 and SUMOylation in tumorigenesis and tumor progression." (PMID 39723246, 2024). "Consistent with our sequencing data, we found elevated level of p-HDAC1 S421/S423 in tumor tissues." (PMID 38652547, 2024). "While tumor size differs between high- and low-expression groups for many HDAC members in many tumors, KIRC is the only one in which the expression of nine HDAC family members, HDAC1/5/8/10/11 and SIRT1/5/6/7, is associated with metastasis." (PMID 39063083, 2024). "Furthermore, correlation analyses between HDAC1 expression, tumor size, and age showed a positive correlation between HDAC1 mRNA levels and tumor size (P<0.05)." (PMID 39512688, 2024). "Thus, gemcitabine strongly inhibits the formation of tumor clusters and proliferation of cells from cultured lung metastasis, perhaps via the elimination of HDAC1-dependent CAFs, which have a high rate of proliferation." (PMID 39001363, 2024). "Importantly, dual inhibition of ERK and HDAC1 significantly ameliorated TGIF2high cell-induced metastasis, which was confirmed based on the tumor burden with H&E staining." (PMID 36647029, 2023). "Given that most tumour cells have altered HDAC activities, it is reasonable to postulate that MAGEA1–SKIP-HDAC1 interaction may contribute to transcriptional alterations that favour tumour cell growth by recruiting HDAC1 to these SKIP target genes." (PMID 36980267, 2023). "Although QST levels in the contralateral brain tissue were significantly lower than those measured in the tumors, they were 12-fold higher than the biochemical IC50 of HDAC1, which ensures target inhibition in infiltrating tumor cells distant from the tumor core." (PMID 37991020, 2023). "HDAC1 not only catalyzes histone acetylation and deacetylation in multisubunit complex but also interacts with retinoblastoma tumor suppressive proteins, which is a key factor in regulating eukaryotic gene expression control and cell proliferation and differentiation." (PMID 36644230, 2023).